FOXD3 (forkhead box D3)
Diseases named in the same sentence as FOXD3 in open-access papers (continued):
Sharing a sentence is not in itself a finding about the gene and the disease.
colorectal cancer (11 papers, 2015 to 2023). A primary or metastatic malignant neoplasm that affects the colon or rectum. "FOXD3 has been found to promote apoptosis in colorectal cancer and non-small cell lung cancer cells through its transcriptional repression." (PMID 36713456, 2022). "A prior study has shown that in colorectal cancer, Foxd3 regulates miR-214 transcription, thereby restraining metastasis and invasion." (PMID 31959866, 2020). "In normal enterocytes, the transcriptional activity of the β-promoter is potently inhibited by the transcription factor forkhead box D3 (FOXD3); in colorectal cancer cells, FOXD3 is epigenetically silenced by methylation, allowing the expression of DCLK1-S." (PMID 29652830, 2018). "Furthermore, miR-214 was found to be downregulated in colorectal cancer, and the transcription factor forkhead box D3 (Foxd3) was positively correlated with miR-21414." (PMID 31959866, 2020). "The Yap get into the nucleus and affected the transcription promotion of FOXD3 on METTL3, resulting in a systematic decrease in the level of m6A modification of overall mRNA in colorectal cancer cells." (PMID 37179374, 2023). "For example, in colorectal cancer, forkhead box D3 acts as a transcription factor of METTL3 and inhibits colorectal cancer metastasis by promoting METTL3 expression." (PMID 36424383, 2022). "Another aspirin-induced upregulated lncRNA, OLA1P2, which is found in human colorectal cancer, is transcriptionally activated by the transcription factor FOXD3 (forkhead box D3)." (PMID 31717266, 2019).
neuroblastoma (8 papers, 2013 to 2024). Neuroblastoma (NB) is the most common solid, extracranial childhood tumor. "Previously, low FOXD3 levels were observed in human neuroblastoma tissues and cell lines suggesting that FOXD3 played a tumor suppressor role." (PMID 28430585, 2017). "To date, the results seems controversies, previous study indicate that FOXD3 exhibits tumor suppressive activity that affects the growth, aggressiveness and angiogenesis of neuroblastoma." (PMID 27027443, 2016). "In addition, FOXD3 transcript levels were lower in more aggressive NB tumors compared with the less aggressive neuroblastic tumors, ganglioneuroblastoma and ganglioneuroma, and FOXD3 transcript levels were inversely associated with international neuroblastoma staging system (INSS) stages." (PMID 24269992, 2013). "However, the function and underlying mechanisms of FOXD3 in the progression of neuroblastoma (NB), an embryonal tumor that is derived from the neural crest, still remain largely unknown." (PMID 24269992, 2013). "The inability to upregulate neural crest specifier genes like FoxD3, Sox10, and Snail2, essential for cell migration and differentiation, might result in the persistence of immature, proliferative cells contributing to tumorigenesis in neuroblastoma." (PMID 39404397, 2024). "NDRG1 expression in neuroblastoma cells can also be induced by the transcription factor forkhead box D3 (FOXD3), which has a lower expression in neuroblastoma tissues and cell lines (SH-SY5Y and SK-N-SH)." (PMID 31485792, 2019).
hepatocellular carcinoma (5 papers, 2014 to 2023). A malignant tumor that arises from hepatocytes. "Further, activation of miR137 transcription by FOXD3 inhibited progression of human hepatocellular carcinoma." (PMID 28430585, 2017). "miR425 through down-regulation of SCAI or forkhead box D3 (FOXD3) promoted proliferation, migration, and hepatocellular carcinoma cell metastasis." (PMID 37582765, 2023). "For example, miR-425-5p is significantly increased in hepatocellular carcinoma (HCC) tissues and is closely related to the poor prognosis of patients with HCC, which as an oncogene promotes the proliferation and migration of HCC cells via RNF11 or FOXD3." (PMID 34686190, 2021).
lung carcinoma (5 papers, 2017 to 2023). "The inhibiting effect of FOXD3 on the drug resistance has also been extensively reported in multiple cancers, including nasopharyngeal carcinoma and lung cancer." (PMID 36627652, 2023). "Silencing FOXD3 in lung cancer cell lines stimulated cell growth and inhibited cell apoptosis." (PMID 27926503, 2017). "In addition, FOXD3 can repress the drug resistance of lung cancer cells in vitro and in vivo, which is in line with our results that overexpression of FOXD3 could attenuate the chemoresistance of OC cells to CP in vivo." (PMID 36627652, 2023).
ovarian carcinoma (5 papers, 2019 to 2023). A malignant neoplasm originating from the surface ovarian epithelium. "FOXD3 is aberrantly regulated in several tumors, but its underlying mechanisms in ovarian cancer (OC) remains largely unknown." (PMID 30858761, 2019). "Demethylated FOXD3 decreases cell migration and proliferation abilities and increases cell apoptosis, even in ovarian cancer." (PMID 35052428, 2021). "In this study, FOXD3 was demonstrated that the degree of methylation and expression in various ovarian cancer cells were changed compared to normal ovarian cells." (PMID 30858761, 2019). "Hypermethylation of FOXD3 correlated with tumor suppressive role (inhibition of proliferation, migration and promotion of apoptosis) in ovarian cancer cells and thus could serve as a potential therapeutic target for diagnosis of ovarian cancer." (PMID 31608277, 2019). "However, the function of FOXD3 in ovarian cancer is still not explicit, which urges us to clarify its mechanism." (PMID 30858761, 2019).
vitiligo (4 papers, 2012 to 2023). Generalized well circumscribed patches of leukoderma that are generally distributed over symmetric body locations and is due to autoimmune destruction of melanocytes. "Patients with vitiligo were found to have a higher frequency of the risk allele FoxD3 (30%) than healthy controls (18.2%)." (PMID 36694854, 2023). "Mutations of the Forkhead transcription factor D3 (FOXD3) are linked to positive thyroid antibodies and the diagnosis of vitiligo." (PMID 34104234, 2021). "However, one study reported an association between vitiligo, an autoimmune skin condition characterized by progressive patchy depigmentation, and the chromosome 1p31 region that includes FOXD3, in a multi-generation family with 13 affected individuals." (PMID 22815627, 2012). "This substitution increases FOXD3 transcription, which may interfere with melanoblast differentiation, creating an autoantigen and predisposing to vitiligo." (PMID 22815627, 2012).
aniridia (2 papers, 2012 to 2017). "FOXD3 was found to be up-regulated, and it is linked with congenital eye deformities such as aniridia, Peter’s anomaly and anophthalmia in humans." (PMID 27188386, 2017). "Here, we report four FOXD3 variants identified primarily in patients with Peters anomaly and aniridia and affecting conserved regions of the FOXD3 protein." (PMID 22815627, 2012). "In all five Peters anomaly/aniridia families reported here, the clinical phenotype was only noted in the proband and mutations in PAX6, the primary aniridia gene were excluded; in two families, the parent carrying the FOXD3 variant had a ‘lazy eye’ (ambylopia) during childhood." (PMID 22815627, 2012). "FOXD3 nonsynonymous variants and their distribution in Peters anomaly/aniridia cases and controls." (PMID 22815627, 2012). "Although enriched in the Peters anomaly/aniridia cohort, the presence of these rare FOXD3 variants in unaffected family members and controls suggests that additional genetic, environmental or stochastic factors may be required for expression of the disease phenotype." (PMID 22815627, 2012).
colitis (2 papers, 2021 to 2025). Inflammation of the colon. "With more severe colitis in the CR+DBZ group, we observed a rebound in FoxD3 staining concomitant with a decline in DCLK1 further indicating an inverse relationship." (PMID 40839695, 2025). "Conversely, as colitis severity increased in the CR+DBZ group, there was a slight decrease in DCLK1 expression accompanied by an increase in FoxD3 status." (PMID 40839695, 2025).
craniosynostosis (2 papers, 2017 to 2023). Craniosynostosis is defined as the premature fusion of one or more cranial sutures leading to secondary distortion of skull shape resulting in skull deformities with a variable presentation. "One of these families, with bicoronal craniosynostosis, harboured a 354 kb deletion downstream of FOXD3, removing a topologically associating domain (TAD) boundary." (PMID 37946251, 2023). "FOXD3 encodes a pioneer winged-helix transcription factor (TF) critical for early embryonic development and is therefore a good candidate for craniosynostosis." (PMID 37946251, 2023). "Another family, with multi-sutural craniosynostosis, had an 11.5 kb duplication upstream of FOXD3 which duplicates a highly conserved enhancer element previously shown to interact with Foxd3 and drive neural crest expression in chick embryos." (PMID 37946251, 2023). "Two further craniosynostosis families were found to have heterozygous SVs flanking a second, novel RD gene, FOXD3, both segregating with disease in their respective families." (PMID 37946251, 2023).
glioma (2 papers, 2014 to 2015). A benign or malignant brain and spinal cord tumor that arises from glial cells (astrocytes, oligodendrocytes, ependymal cells). "Immunohistochemistry showed FOXD3 protein was mainly expressed in the nuclear of glioma and normal brain cells." (PMID 26011451, 2015). "The results revealed FOXD3 mRNA expression was significantly decreased in glioma tissues in comparison to normal brain (P<0.001)." (PMID 26011451, 2015). "Depletion of FOXD3 expression promoted glioma cell proliferation and inhibited serum starvation-induced apoptosis, whereas overexpression of FOXD3 inhibited glioma cell proliferation and promoted serum starvation-induced apoptosis." (PMID 26011451, 2015). "Western blotting analysis further showed that glioma had lower FOXD3 protein expression than normal brain (P = 0.030)." (PMID 26011451, 2015). "Moreover, we explored the effects of FOXD3 expression on proliferation and apoptosis of glioma cells in vitro." (PMID 26011451, 2015). "Therefore, the biological roles and clinical significance of FOXD3 expression in grade IV gliomas need further investigation in larger population." (PMID 26011451, 2015). "In addition, our in vitro analyses showed that FOXD3 inhibited the proliferation of glioma cells and promoted starvation-induced cell apoptosis." (PMID 26011451, 2015). "Furthermore, we examined the protein expression levels of FOXD3 in five glioma cell lines including LN405, U118, SW1080, T98M and U87MG cells." (PMID 26011451, 2015). "We further explored the prognostic value of FOXD3 in glioma." (PMID 26011451, 2015). "Moreover, in vitro studies demonstrated that FOXD3 inhibited proliferation and enhanced starvation-induced apoptosis in glioma cells." (PMID 26011451, 2015). "In addition, we further examined the effects of FOXD3 on the proliferation and serum starvation-induced apoptosis of glioma cells." (PMID 26011451, 2015). "Similarly, we demonstrated a decrease of FOXD3 expression in HGGs and overexpression of FOXD3 significantly may inhibit the proliferation of glioma cells partly by promoting cell apoptosis under stress." (PMID 26011451, 2015). "The molecular mechanisms by which FOXD3 inhibits the growth of glioma remain unknown." (PMID 26011451, 2015). "However, high FOXD3 expression was significantly with better PFS in patients with WHO grade III diseases but not grade IV gliomas, probably due to the limited sample size of this subpopulation." (PMID 26011451, 2015).
lymphoma (2 papers, 2019 to 2023). A malignant (clonal) proliferation of B- lymphocytes or T- lymphocytes which involves the lymph nodes, bone marrow and/or extranodal sites. "Also, the mutation effects on TF binding at the promoter of two important FL genes (BCL6 and BCL2) were recovered: for example, regulatory activities of two TFs (FOXD2 and FOXD3) on BCL6 and BCL2 were confirmed previously by knockdown experiments in SUDHL4 lymphoma cell." (PMID 31001324, 2019).
nasopharyngeal carcinoma (2 papers, 2023). A carcinoma arising from the nasopharyngeal epithelium. "FOXD3 expression is downregulated in CP-resistant nasopharyngeal carcinoma cells and it can promote the expression of miR-26b which sensitizes nasopharyngeal carcinoma cells to CP." (PMID 36627652, 2023).
renal carcinoma (2 papers, 2013 to 2019). A carcinoma arising from the epithelium of the renal parenchyma or the renal pelvis. "Soft agar and transwell assays indicated that FOXD3 might exert tumor suppressive and oncogenic roles in cervix cancer and renal cancer, respectively." (PMID 24269992, 2013).
thyroid cancer (2 papers, 2015 to 2017). "Next, we analyzed the relationship between FOXD3 expression and thyroid cancer cell apoptosis by analyzing Caspase-3 activity in FOXD3 silenced SW1736 and K18 cells compared to controls." (PMID 28430585, 2017). "Since the MAPK pathway is upregulated in thyroid cancer because of activating BRAF mutations and others, we evaluated the effects of FOXD3 knockdown on ERK1/2." (PMID 28430585, 2017). "In this study, we postulated that the FOXD3 transcription factor may play a significant role in analplastic thyroid cancer growth based on studies in other cancers." (PMID 28430585, 2017). "Therefore, we investigated the mechanistic role of FOXD3 in thyroid cancer progression by evaluating ATC cell lines and patient tissue samples." (PMID 28430585, 2017).
thyroid tumor (2 papers, 2017 to 2023). A benign or malignant neoplasm affecting the thyroid gland. "Clinical studies also showed FOXD3 was high expressed in normal samples campared with tumor samples and its expression was negatively correlated to p-ERK, suggesting that FOXD3 is critical for thyroid tumor genesis and progression." (PMID 28430585, 2017). "Similarly, we observed decreased FOXD3 expression in thyroid tumor patient tissues compared to normal tissues." (PMID 28430585, 2017).
acute myeloid leukemia (1 paper, 2021). Acute myeloid leukemia (AML) is a group of neoplasms arising from precursor cells committed to the myeloid cell-line differentiation. "In a related study, overexpression of LINC00449 could inhibit acute myeloid leukemia cell invasion and cell proliferation in vitro and in vivo, and the LINC00449/miR-150/FOXD3 signaling pathway may be a novel prognostic biomarker or therapeutic target for the treatment of acute myeloid leukemia." (PMID 34819945, 2021).
anaplastic thyroid cancer (1 paper, 2017). "Our study demonstrated that FOXD3 knockdown increased human anaplastic thyroid cancer cell proliferation and enhanced invasivess and EMT attributes and reduced cancer cell apoptosis." (PMID 28430585, 2017). "First, we observed low FOXD3 expression in anaplastic thyroid cancer cell lines (SW1736 and K18) compared to the normal thyroid cell line (Nthy-ori 3-1)." (PMID 28430585, 2017). "This suggested that low FOXD3 enhanced EMT and metastasis of anaplastic thyroid cancer cells." (PMID 28430585, 2017). "However, the role of FOXD3 in anaplastic thyroid cancer (ATC) is not clear." (PMID 28430585, 2017).
autoimmune disease (1 paper, 2019). A disorder resulting from loss of function or tissue destruction of an organ or multiple organs, arising from humoral or cellular immune responses of the individual to their own tissue constituents. "Forkhead Box D3 (FOXD3) gene is a representative of the Fox transcription factor family, which is mainly involved in autoimmune disease." (PMID 30781778, 2019).
B-cell acute lymphoblastic leukemia (1 paper, 2025). A neoplasm of lymphoblasts committed to the B-cell lineage, typically composed of small to medium-sized blast cells. "Our study highlights the complex immune regulatory network involved in B-cell acute lymphoblastic leukemia (B-ALL), focusing on the interplay between VISTA, CD244, CD48, FOXD3, and PVRL2." (PMID 40610562, 2025).
cervix cancer (1 paper, 2013). "However, over-expression of FOXD3 into cervix cancer HeLa cells did not affect the NDRG1 expression, although resulting in decreased in vitro growth and invasion capabilities." (PMID 24269992, 2013).
colon adenocarcinoma (1 paper, 2017). "Next, we knocked down FOXD3 expression in HCT116 and Caco-2 human colon adenocarcinoma cell lines." (PMID 27926503, 2017).
embryonal carcinoma (1 paper, 2022). A non-seminomatous malignant germ cell tumor characterized by the presence of large germ cells with abundant cytoplasm resembling epithelial cells, geographic necrosis, high mitotic activity, and pseudoglandular and pseudopapillary structures formation. "Our analysis suggested that the expression of CDX4 and FOXD3 from TGCT cohort was significantly higher in embryonal carcinoma than in seminoma, which was verified by qRT-PCR experiments." (PMID 36713456, 2022). "Among expression-related genes, CDX4 and FOXD3 were significantly overexpressed in embryonal carcinoma, whereas CUX2 and RPS6KA5 were increased in seminoma." (PMID 36713456, 2022).
endometriosis (1 paper, 2024). The growth of functional endometrial tissue in anatomic sites outside the uterine body. "Within these findings, FOXD3 emerged as a pivotal regulator of gene expression distinct to the secretory phase/endometriosis." (PMID 39079132, 2024). "Notably, FOXD3 exhibited dynamic expression patterns in healthy endometrium and showed significant differential expression in cases of endometriosis." (PMID 39079132, 2024).
epilepsy (1 paper, 2023). A brain disorder characterized by episodes of abnormally increased neuronal discharge resulting in transient episodes of sensory or motor neurological dysfunction, or psychic dysfunction. "The involvement of lncRNA PVT1 in epilepsy has revealed its role in promoting neuroinflammation by modulating the miR-488-3p/FOXD3/SCN2A axis." (PMID 37653173, 2023). "The involvement of lncRNA PVT1 in epilepsy has revealed its role in promoting apoptosis in neuronal cells by modulating the miR-488-3p/FOXD3/SCN2A axis." (PMID 37653173, 2023).
head and neck cancer (1 paper, 2020). A primary or metastatic malignant neoplasm affecting the head and neck. "Kaplan–Meier analysis revealed that FOXD1, as compared to FOXD2, FOXD3 and FOXD4, upregulation more significantly (p = 0.008) predicts a poor overall survival rate in TCGA head and neck cancer patients." (PMID 32967107, 2020). "We next evaluated the prognostic significance of FOXD1, FOXD2, FOXD3 and FOXD4 in TCGA head and neck cancer patients." (PMID 32967107, 2020). "Moreover, except FOXD3, we found that FOXD1, FOXD2 and FOXD4 are more significantly (p < 0.01) upregulated in primary tumor tissue compared to normal adjacent tissues derived from TCGA head and neck cancer patients." (PMID 32967107, 2020).
high-grade gliomas (1 paper, 2015). "However, the expression and its potential biological roles of FOXD3 in high-grade gliomas (HGGs) remain unknown." (PMID 26011451, 2015).
Hypertension (1 paper, 2025). The presence of chronic increased pressure in the systemic arterial system. "At the genetic level, our independent differential and prognostic analyses identified FOXD3, F10, and SLC12A5 as genes shared between thyroid cancer and hypertension." (PMID 40785195, 2025). "Moreover, our findings underscore the critical role of differentially expressed genes, particularly FOXD3, F10, and SLC12A5, in the pathogenesis of both hypertension and thyroid cancer." (PMID 40785195, 2025).
infectious colitis (1 paper, 2025). A viral or bacterial infectious process affecting the large intestine. "Following CR-induced infectious colitis in mice, IMC revealed accumulation of DCLK1-S in the colons of infected mice that inversely correlated with DCLK1-S repressor FoxD3 (Forkhead Box D3)." (PMID 40839695, 2025).